ATP8B3 (ATPase phospholipid transporting 8B3)
Description:
P4-ATPase flippase which catalyzes the hydrolysis of ATP coupled to the transport of aminophospholipids from the outer to the inner leaflet of various membranes and ensures the maintenance of asymmetric distribution of phospholipids. Phospholipid translocation also seems to be implicated in vesicle formation and in uptake of lipid signaling molecules. May be responsible for the maintenance of asymmetric distribution of phosphatidylserine (PS) in spermatozoa membranes. Involved in acrosome reactions and binding of spermatozoa to zona pellucida.
Synonyms: ATPIK
Tractability: Antibody: UniProt predicts a signal peptide or a membrane-spanning region; its Gene Ontology location is reachable by antibodies, with medium confidence. PROTAC: ubiquitination databases record sites on it.
Gene: Protein-coding gene on chromosome 19 (1,782,075 to 1,812,276, reverse strand). Ensembl gene ENSG00000130270.
Subcellular location: Cytoplasmic vesicle, secretory vesicle, acrosome membrane; Endoplasmic reticulum membrane
Pathways (Reactome):
Transport of small molecules: Ion transport by P-type ATPases
Gene Ontology:
Molecular function: ATPase-coupled intramembrane lipid transporter activity; phosphatidylserine floppase activity; ATP binding; ATP hydrolysis activity; magnesium ion binding; nucleotide binding
Biological process: Golgi organization; phospholipid translocation; phospholipid transport
Cellular component: endoplasmic reticulum membrane; membrane; phospholipid-translocating ATPase complex; trans-Golgi network; acrosomal membrane; acrosomal vesicle; endomembrane system
Genetic constraint (gnomAD): Loss-of-function variants: 143 observed, 128.3 expected, observed/expected ratio (o/e) 1.11, 90% interval 0.97 to 1.28. The upper end of that interval is the gene's LOEUF score, 1.28, which puts it in group 5 of 6, group 1 being the genes least tolerant of losing a copy. Missense variants: 1,874 observed, 1,682.5 expected, observed/expected ratio (o/e) 1.11, 90% interval 1.07 to 1.16. Synonymous variants: 765 observed, 691.26 expected, observed/expected ratio (o/e) 1.11, 90% interval 1.04 to 1.17.
Homologues: Orthologues: chimpanzee ATP8B3 (99% identical), macaque ATP8B3 (92% identical), pig ATP8B3 (70% identical), rat Atp8b3 (67% identical), mouse Atp8b3 (65% identical), tropical clawed frog atp8b3 (46% identical), zebrafish atp8b3 (39% identical), Drosophila melanogaster CG4301 (25% identical), Drosophila melanogaster CG9981 (24% identical), Drosophila melanogaster CG31729 (22% identical), Caenorhabditis elegans tat-6 (21% identical), Caenorhabditis elegans tat-5 (21% identical). Paralogues in human: ATP8B1 (43% identical), ATP8B2 (40% identical), ATP8B4 (39% identical), ATP8A2 (32% identical), ATP8A1 (31% identical), ATP10D (31% identical), ATP10A (30% identical), ATP10B (29% identical), ATP11A (26% identical), ATP11B (25% identical), ATP11C (24% identical), ATP9A (23% identical), and 1 more.
Diseases named in the same sentence as ATP8B3 in open-access papers:
ATP8B3 is named in the same sentence as 10 diseases in open-access papers, as found by Europe PMC text mining. Sharing a sentence is not in itself a finding about the gene and the disease. The quoted sentences say what the papers report.
Insulin resistance (2 papers, 2019 to 2025). Increased resistance towards insulin, that is, diminished effectiveness of insulin in reducing blood glucose levels. "For example, maternal Omega-3 PUFA intake during pregnancy affects offspring DNA methylation, influencing genes like MSTN, IFNA13, ATP8B3, and GABBR2, which are linked to insulin resistance, adiposity, and immune responses." (PMID 40507105, 2025). "Genes such as MSTN, IFNA13, ATP8B3, and GABBR2 showed methylation changes, potentially influencing insulin resistance, adiposity, and innate immune response in offspring." (PMID 40507105, 2025).
diabetes (1 paper, 2022). "DHDH is involved in the detoxication of trans-dihydrodiol and carcinogenic metabolites of polycyclic aromatic hydrocarbons; SUCNR1 is related to conditions such as hypertension, diabetes, and obesity, whereas ATP8B3 is involved in aminophospholipid transport in the liver." (PMID 36542226, 2022).
lipid metabolism disorder (1 paper, 2023). "Conversely, among the top 10 proteins of HML pattern, four were related to lipid metabolism, including APOA1, KRT17, B2R8I2, and ATP8B3, demonstrating continuously increased lipid metabolism disorder with the increase of bacterial loads." (PMID 37908762, 2023).
lung carcinoma (1 paper, 2022). "The orthologues were related to DHDH, ATP8B3, and P2RY1 genes, expressed in the lipid membrane, and directly related to skin and lung cancer genes (APP and APPBP2), suggesting that they may share mechanisms among these diseases." (PMID 36542226, 2022).
cancer (2 papers, 2023 to 2025). A tumor composed of atypical neoplastic, often pleomorphic cells that invade other tissues. "Having shown that ATP8B3, FOXR2, FRG2 and HIST1H4A KOs increased paclitaxel resistance and cancer stemness in vitro, we next investigated whether these KOs could also regulate paclitaxel effects in vivo." (PMID 37932309, 2023). "Interestingly, we found several of these genes (ATP8B3, FOXR2, FRG2, HIST1H4A) to act as cancer stemness regulators, able to regulate cancer stem cell self-renewal activity and expression of the endothelial protein C receptor (EPCR), a specific stemness marker for TNBC." (PMID 37932309, 2023). "We found that several of these genes (ATP8B3, FOXR2, FRG2, HIST1H4A) act as cancer stemness negative regulators." (PMID 37932309, 2023). "Collectively, and combined with our findings, showing increased paclitaxel resistance in these gene KOs, our results define ATP8B3, FOXR2, FRG2 and HIST1H4A as cancer stemness negative regulators, consistent with a role for these genes as potential drug (paclitaxel) sensitizers." (PMID 37932309, 2023).
tumor (2 papers, 2021 to 2023). "There were 11 DEGs associated with tumor cell differentiation and dedifferentiation between EGFP- CD44-/CD24- cells and EGFP+ CSCs and they included RHBDL2, HIST1H4H, DSCC1, ZNF710, ATP8B3, and others." (PMID 34318746, 2021). "We found that ATP8B3, FOXR2, FRG2 and HIST1H1A gene silencing significantly enhanced TNBC cells tumor-initiating capacity as well as expression of the TNBC stemness marker, EPCR, thereby defining a new role for these genes in stemness regulation." (PMID 37932309, 2023). "Moreover, ATP8B3, FOXR2, FRG2 also decreased tumor response to paclitaxel in vivo, in preclinical models of TNBC tumorigenesis." (PMID 37932309, 2023).
ATP8B3 also shares sentences with these, for which no sentence is quoted: lung adenocarcinoma (2 papers); breast carcinoma (1); Hypertension (1); Obesity (1).